ARG1 (arginase 1)
Diseases named in the same sentence as ARG1 in open-access papers (continued):
Sharing a sentence is not in itself a finding about the gene and the disease.
glioma (continued). "Exploring various public datasets we found the elevated expression of ARG1 and ARG2 in high grade gliomas, in particular in highly aggressive GBMs." (PMID 34504786, 2021). "TGFB1, VEGFA, ARG1, FGL2 and IL10 are secreted immunosuppressive factors in glioma, while CD95L and CD70 are glioma cell‐surface immunosuppressive factors." (PMID 33611848, 2021). "A novel, selective ARG1/2 inhibitor - OAT-1746 blocked microglia-dependent invasion of U87-MG and LN18 glioma cells in a Matrigel invasion assay better than reference compounds, without affecting the cell viability." (PMID 34504786, 2021). "Using transcriptomic data from The Cancer Genome Atlas (TCGA), we examined ARG1 and ARG2 expression in human gliomas of different WHO grades II, III, IV." (PMID 34504786, 2021). "Depending on the level of COX-2, PGE2 promoted the secretion of IL-8 from glioma cells through autocrine, advanced the migratory response of M-MDSCs to MCP-1, and promoted the expression of ARG1 in PMN-MDSCs." (PMID 34211978, 2021). "Overall, these results confirm high ARG1 and ARG2 expression in human malignant cells and glioma-infiltrating monocytes/macrophages." (PMID 34504786, 2021). "JWH133 treatment also significantly increased the mRNA level of M2 subtype markers CD206, Arg1, and Ym1 and decreased the mRNA level of M1 subtype markers CD68, CD86, and iNOS in the tissues around glioma, in vivo (*P < 0.05 and **P < 0.01 vs. Vehicle)." (PMID 33330047, 2020). "Increased plasma levels of arginase 1 and G-CSF secreted from MDSCs contribute to enhancement of MDSC suppressor function and its accumulation in glioma sites." (PMID 31225500, 2019). "After the uptake of EV derived from a Lewis lung carcinoma (LLC) and glioma, MDSC displayed an increased expression of immunosuppressive molecules like arginase-1 (ARG1) and programmed death ligand 1 (PD-L1)." (PMID 29552012, 2018). "Most of the Arg1 expression was seen in infiltrating MPs, which were more prevalent in this model than the GL261 gliomas." (PMID 27936099, 2016). "Furthermore, studies indicate that ARG-1 inhibits AKT activity by directly interacting with the Cys310 residue of AKT, thereby facilitating glioma progression." (PMID 40342932, 2025). "The higher contribution of monocytes-derived macrophages to elevated Arg1 levels in mouse gliomas, rather than microglia, is consistent with previous findings." (PMID 40281508, 2025). "In vitro experiments demonstrate that glioma cell-derived Wnt3a triggers the activation of the Wnt/β-catenin pathway in microglia, induces them to express ARG-1 and STI1, shifts them to the M2 phenotype, enhances tumor infiltration, invasion, growth and the crosstalk between microglia and gliomas." (PMID 37700840, 2023). "Arginase-1 (ARG1) expression is upregulated in M2-TAM in several mouse tumor models, while glutamate transport and other metabolic genes are upregulated in M1-TAM in mouse glioma." (PMID 37138860, 2023). "In the cancer-immunity cycle, we found genes that inhibit the cycle, including the glioma-secreted and cell-surface immunosuppressive factors, TGFB1, VEGFA, ARG1, IL10, and CD70, they were highly expressed in the high-risk group and were positively correlated with the risk score." (PMID 37891828, 2023). "Our initial finding was that hypoxic glioma‐derived EVs could promote macrophages M2 polarization, as evidence by decreased expression of iNOS and TNF‐α as well as elevated expression of Arg‐1 and IL‐10." (PMID 36052751, 2022). "The administration of OAT-1746 or anti-PD-1 treatment did not change the accumulation of Iba1+ and Arg1+ cells in experimental gliomas." (PMID 34504786, 2021). "In the context of a high-grade brain tumor model where glioma-associated macrophages/microglia (GAMs) were M2 polarized, CSF1R inhibitors were found to decrease expression of M2 markers in GAMs such as Arg1 and Mrc1 (CD206) without influencing their numbers." (PMID 34281564, 2021).
glioma (continued). "Thus, we analyzed the expression of a panel of common M1 (IL-1b, IL-12, iNOS, TNFα) and M2 (TGFβ, IL-10, ARG1) phenotype markers and the immune suppressive PD-L1 (CD274) in control and Pdpn-deleted BMDM co-cultivated with four different glioma cell lines." (PMID 30972297, 2019). "In the case of GBs, glioma cells are able to stimulate GAMs to produce immunosuppressive molecules, such as IL-10, metalloproteinases (MMPs), chemokines as monocyte chemotactic protein-1 (CCL2), and ARG-1, that stimulate the tumor growth." (PMID 30123112, 2018). "In our work we provide evidence that GSC-derived exosomes are involved in the conversion of monocytes to arginase-1- and IL-10-producing Mo-MDSC cells that contribute to T cells immunosuppression without the necessity of direct contact between monocytes and glioma cells." (PMID 28107450, 2017). "Antitumor immune responses in aPD-1- and RGD + aPD-1-treated gliomas evolved with time, as at an earlier time point 21 DPI, the tumor volume did not change upon treatment, and the myeloid compartment was dominated by Arg1+ and PD-L1+ immunosuppressive macrophages." (PMID 40281508, 2025). "In a murine glioma model where Csf1 expression is increased approximately 2.5-fold compared to normal brain, CSF1R inhibitors decrease expression of M2 markers including Arg1 in GAMs, suggesting that increased CSF1/CSF1R signaling can promote polarization toward a M2 phenotype in the diseased CNS." (PMID 34281564, 2021). "Of note, although arginase 1 gene expression was significantly reduced in CD11b+ cells isolated from glioma-bearing mice upon sEVs treatment, the result was not confirmed on IL4-stimulated microglial cells or by the release of NO by BV2 cells, suggesting the need of further investigations." (PMID 34440835, 2021). "Interestingly, we found elevated levels of ARG1-positive myeloid cells predominantly inside the metastatic tumour, consistent with previous reports showing similar results in 4T1 and PyMT-BO1 metastatic breast tumours as well as colon carcinoma, lymphoma and melanoma and glioma mouse models." (PMID 37980483, 2023). "Furthermore, by qPCR, IHC, and Western blotting, in different pathological grades of glioma tissues, we found a significant increase in the expression levels of M2-type macrophage-specific markers with increasing tumor grade, including CD206, CD163, ARG1, CD115, and IL-10." (PMID 36033495, 2022). "In contrast to MPs, however, Arg1 expression in resident MG was delayed and occurred later during tumor growth and was independent of TAM infiltration into gliomas." (PMID 27936099, 2016).
Sepsis (59 papers, 2015 to 2026). Sepsis is defined as life-threatening organ dysfunction caused by a dysregulated host response to infection. "Concordantly, increased expression of Arg1, Mrc1 and Retnla (encoding Fizz-1) was found in a CD11b+ macrophage-enriched population isolated from the lungs of sepsis-surviving mice by day 10 after CLP." (PMID 28374774, 2017). "Similar to the effects of iNOS or Arg1 inhibition in monocytes, LdhaΔMo mice exhibited a reversal of the protective effects of regular exercise on body temperature drop and body weight loss during sepsis." (PMID 41398160, 2025). "ARG1 in particular has been identified by other groups as a good biomarker for sepsis diagnosis, specifically associated with neutrophil activity a component of which may be from a myeloid-derived suppressor cell (MDSC) phenotype." (PMID 38332914, 2023). "In addition, the expression of M2 marker Arg-1 in injured kidneys was significantly increased in the CXCL14 − Tg + CLP group even in the early stage of sepsis-associated AKI as compared with the CLP group (p < 0.001, respectively)." (PMID 32317861, 2020). "Notably, ARG1 was the only overlapped gene in both results, suggesting that it may be more closely associated with sepsis." (PMID 35739592, 2022). "However, the upregulation of arginase-1 in MDSCs has been observed following trauma and sepsis, which may result in loss of arginine." (PMID 29670613, 2018). "Arg1 inhibition in monocytes abolished the protective effects of exercise on reducing body temperature decline, weight loss, IL-1β and TNF-α levels and sepsis-induced myocardial injury." (PMID 41398160, 2025). "Consistent clustering of Sepsis samples in GSE65682 dataset was conducted based on four diagnostic genes (APRT, ARG1, UMPS, LDHB) associated with patient survival." (PMID 40774030, 2025). "All of this information indicates that ARG1 has potential as a biomarker for the accurate diagnosis and prediction of Sepsis." (PMID 40774030, 2025). "It was found that patients with high expression of ARG1 in Sepsis patients had a poor prognosis, which is coincides with this." (PMID 40774030, 2025). "Studies have shown that ARG1 is a kind of promising biological marker in the diagnosis of Sepsis and prognosis." (PMID 40774030, 2025). "The authorsfurther verified high expression of ARG1 in the peripheral blood of Sepsis patients by qRT-PCR." (PMID 40774030, 2025). "Univariate and multivariate COX analysis based on four diagnostic genes and clinicopathological factors showed that the ARG1 gene and age were independent prognostic factors of Sepsis." (PMID 40774030, 2025). "Our study underscores the significant potential of biomarkers such as MMP8, MMP9, and ARG1 in advancing the early diagnosis and targeted treatment of sepsis." (PMID 39560539, 2024). "ARG1 and HP play different but complementary roles in the pathophysiology of SAP- associated sepsis." (PMID 39364223, 2024). "Conversely, sepsis samples consistently exhibited high ARG1 expression and low CCR7 expression, while normal samples consistently displayed high CCR7 expression and low ARG1 expression across the various datasets." (PMID 39710434, 2024). "This study’s bioinformatics analysis has identified significant alterations in the expression of genes such as MMP8, MMP9, and ARG1 in the granulocytes of patients with sepsis." (PMID 39560539, 2024). "The subsequently experiments suggested that sepsis caused upregulated expression of F4/80, iNOS and CD86, as well as downregulated expression of Arg‐1 and CD206 in renal tissues of mice were reversed by Deh treatment." (PMID 38629726, 2024). "In this study, the upregulation of arginase ARG1 in transcriptomic results was consistent with the increased arginine consumption observed in patients with sepsis." (PMID 37445637, 2023). "In this set of data, the expression level of ARG1 in severe sepsis and lethal sepsis was significantly higher than that in uncomplicated sepsis." (PMID 35739592, 2022).
Sepsis (continued). "In order to verify the role of ARG1 in sepsis, more GSE datasets were brought into our analysis and validation system." (PMID 35739592, 2022). "Through hydrolyzing arginine and disturbing eNOS activity, up-regulation of ARG1 contributes to vasodilation dysfunction in different stages of sepsis." (PMID 35739592, 2022). "All these informations indicated the potential of ARG1 as a biomarker in accurate diagnosis, prediction and treatment of sepsis." (PMID 35739592, 2022). "We observed significant downregulation of FIZZ1 and Arg1, concomitant with a decrease in the count of CD 163-positive cells, which was maintained for up to 3 days post-sepsis." (PMID 36035473, 2022). "Sorted MDSCs from sepsis patients showed increased IL-10, ARG1, and iNOS expression; however, a significant increase was observed in IL-10 compared to that in HCs (p = 0.016)." (PMID 35720398, 2022). "The quantitative real-time PCR showed that the transcription abundance of AGR1 increased dramatically in the peripheral blood of septic mice, demonstrating that ARG1 is highly correlated with sepsis and have potential to act as a key biomarker." (PMID 35739592, 2022). "After sepsis, MDSCs increase the expression of arginase 1 (ARG1), which lowers the arginine concentration in the microenvironment." (PMID 35924237, 2022). "In sepsis patients, MDSCs had increased IL-10, Arg1, and iNOS mRNA levels (p = 0.016, p = 0.043, and p = 0.045)." (PMID 35720398, 2022). "A study has demonstrated that in patients with sepsis, early expansion of ARG1-producing G-MDSCs correlated with increased T cell dysfunction and increased susceptibility to secondary infections in the surgical intensive care unit." (PMID 35911709, 2022). "In parallel, EPOR activation downregulated iNOS and IL-1β but increased Arginase-1 and shifted macrophage polarization into an anti-inflammatory stage, to properly balance against sepsis proinflammation." (PMID 34831360, 2021). "Gene differential expression analysis between healthy controls and sepsis showed that genes such as ARG1, CD177, MMP8 and C19orf59 were upregulated." (PMID 33032623, 2020). "Genes that were expressed at high levels in MBC and sepsis patients compared with HC N cells were relevant to immunosuppression and metastasis (ARG1, MMP8, TLR5, and CD177) (green)." (PMID 32958605, 2020). "This study demonstrates the role of significant and widespread immune activation (IL1R2, MMP9), along with oxidative stress (ARG1) and the recruitment of neutrophils, in sepsis (ELANE, MPO)." (PMID 31817302, 2019). "A deregulated immune response is one of the major characteristics of sepsis, and ARG1 metabolism is a regulator of it." (PMID 31817302, 2019). "Increased plasma ARG1 activity depletes the concentrations of L-arginine, the substrate for NO synthesis, leading to vascular dysfunction during severe sepsis and suppressed NO-mediated microbicidal effects." (PMID 31817302, 2019). "They found that, compared to MDSCs isolated three days after the onset of sepsis, MDSCs isolated 10 days after sepsis were highly functional, with robust cytokine and ROS production and arginase 1 activity." (PMID 31075836, 2019). "•ARG1 and age are independent prognostic factors for sepsis outcomes." (PMID 40774030, 2025). "The expression increased within 72 h of sepsis induction, which indicates the importance of early intervention that should be based on decreasing iron overload and driving macrophage polarization to M2 type with Arg1+ and Fizz1+ phenotypes." (PMID 39949667, 2025). "The high expression of ARG1 can consume a large amount of L-arginine and interfere with eNOS activity, which will affect NO synthesis in the eNOS pathway of arginine and lead to vasodilatory dysfunction in different stages of Sepsis." (PMID 40774030, 2025).
Sepsis (continued). "Furthermore, MDSCs, significantly expanded in sepsis, strongly inhibit effector T cells while relatively promoting Treg differentiation and function by producing Arg1, iNOS, ROS, TGF-β, IL-10 and expressing PD-L1." (PMID 40806563, 2025). "Notably, the prognostic predictive function of the ARG1 gene for sepsis lacks adequate in vitro and in vivo experimental validation, which limits the clinical applicability of the related research findings." (PMID 40774030, 2025). "•Identified 4 diagnostic genes (APRT, ARG1, UMPS and LDHB) for sepsis prognosis." (PMID 40774030, 2025). "STAT1, -5, and -6 are also important in the regulation of arginase activity, although this may be more pertinent for cancer than sepsis based on the subdued level of ARG1 expression in MDSCs identified from our septic patients." (PMID 38720891, 2024). "Finally, ARG1 and HP were identified as valuable diagnostic markers and nomogram maps were developed to improve early identification of SAP-associated sepsis." (PMID 39364223, 2024). "In addition, the expression of ARG1 in neutrophils is significantly upregulated in sepsis patients, and inhibition of ARG1 can significantly restore the immune function of CD8+T cells." (PMID 39364223, 2024). "Likewise, Myeloid-derived suppressor cells (MDSCs) are also involved in sepsis-induced immunosuppression throughout the production of arginase 1 and contribute to T-cell dysfunction." (PMID 38235139, 2023). "Importantly, levels of MDSCs mediators and the expression of genes with immunosuppressive functions, such as S100A8/A9, S100A12, and ARG1, are highly elevated in patients with sepsis." (PMID 38235139, 2023). "Considering the high expression of ARG1 in sepsis, we next investigated whether ARG1 played a role in distinguishing sepsis from diseases with similar symptoms." (PMID 35739592, 2022). "ARG1 was found to be the only one overlapped gene in both results, indicating that this gene was not only highly correlated with the clinical phenotype of sepsis, but also played a hub role in protein-protein interactions." (PMID 35739592, 2022). "In conclusion, our study showed ARG1 could act as a potential “multifunctional” biomarker to provide more information for the diagnosis of sepsis, prediction of severity, and judgement of the responsiveness to supportive therapy." (PMID 35739592, 2022). "Furthermore, since the GSE63042 dataset contained 28 lethal sepsis cases, 21 severe sepsis cases, and 24 uncomplicated sepsis cases, we further revealed the role of ARG1 in discriminating the severity of this disease." (PMID 35739592, 2022). "Since the transcription level of ARG1 is significantly high in sepsis, Q-PCR could be a promising method for rapid test of ARG1 as a biomarker." (PMID 35739592, 2022). "Collectively, ARG1 could worsen immunosuppression and vascular dysfunction during sepsis, leading to the poor prognosis, which is in accordance with our findings." (PMID 35739592, 2022). "Consistently, a meta-anslysis also reported the upregulation of ARG1 during sepsis." (PMID 35739592, 2022). "ascribed elevated MMP9 as well as ARG1 expression in whole blood during sepsis to MDSCs, which may also have been present in our CD15 cell fraction." (PMID 35844509, 2022). "Moreover, ARG1 expression was also found up-regulated in patients with septic shock (20 cases) compared with patients with general sepsis (19 cases) based on the dataset from Germany." (PMID 35739592, 2022). "H3K18la-mediated anti-inflammatory effects, such as IL-10 overexpression, may play an important role in the anti-inflammatory function of macrophages as well as Arg1 expression in sepsis." (PMID 35069560, 2021). "H3K18la might mediate inflammatory cytokine expression and Arg1 overexpression and stimulate the anti-inflammatory function of macrophages in sepsis." (PMID 35069560, 2021). "We tested whether increasing Hotairm1 levels in early sepsis Gr1+CD11b+ MDSCs could affect Arginase 1 and IL-10 expressions." (PMID 33335790, 2020).